TAB1 (TGF-beta activated kinase 1 (MAP3K7) binding protein 1)
Description:
Key adapter protein that plays an essential role in JNK and NF-kappa-B activation and proinflammatory cytokines production in response to stimulation with TLRs and cytokines. Mechanistically, associates with the catalytic domain of MAP3K7/TAK1 to trigger MAP3K7/TAK1 autophosphorylation leading to its full activation. Similarly, associates with MAPK14 and triggers its autophosphorylation and subsequent activation. In turn, MAPK14 phosphorylates TAB1 and inhibits MAP3K7/TAK1 activation in a feedback control mechanism. Also plays a role in recruiting MAPK14 to the TAK1 complex for the phosphorylation of the TAB2 and TAB3 regulatory subunits.
Synonyms: MAP3K7IP1; 3'-Tab1
Tractability: Small molecule: a structure with a bound ligand is known; a high-quality ligand is known; it has a high-quality binding pocket; it belongs to a druggable protein family. Antibody: UniProt places it where antibodies can reach, with high confidence. PROTAC: UniProt records ubiquitination sites on it; ubiquitination databases record sites on it; its protein half-life has been measured; a small molecule that binds it is known.
Gene: Protein-coding gene on chromosome 22 (39,399,778 to 39,437,060, forward strand). Ensembl gene ENSG00000100324.
Subcellular location: Cytoplasm, cytosol; Endoplasmic reticulum membrane
Pathways (Reactome):
Immune System: Alpha-protein kinase 1 signaling pathway; CLEC7A (Dectin-1) signaling; FCERI mediated NF-kB activation; IRAK2 mediated activation of TAK1 complex; IRAK2 mediated activation of TAK1 complex upon TLR7/8 or 9 stimulation; Interleukin-1 signaling; JNK (c-Jun kinases) phosphorylation and activation mediated by activated human TAK1; NOD1/2 Signaling Pathway; TAK1-dependent IKK and NF-kappa-B activation; TICAM1,TRAF6-dependent induction of TAK1 complex; TRAF6-mediated induction of TAK1 complex within TLR4 complex; activated TAK1 mediates p38 MAPK activation
Disease: SARS-CoV-2 activates/modulates innate and adaptive immune responses
Metabolism of proteins: Ub-specific processing proteases
Signal Transduction: TNFR1-induced NF-kappa-B signaling pathway
Gene Ontology:
Molecular function: molecular adaptor activity; protein binding; protein serine/threonine kinase activator activity; kinase activator activity; mitogen-activated protein kinase p38 binding; protein serine/threonine phosphatase activity; protein-containing complex binding
Biological process: canonical NF-kappaB signal transduction; non-canonical NF-kappaB signal transduction; positive regulation of cGAS/STING signaling pathway; regulation of MAPK cascade; positive regulation of intracellular signal transduction; signal transduction
Cellular component: cytoplasm; endoplasmic reticulum; endoplasmic reticulum membrane; serine/threonine protein kinase complex; cytosol; endosome membrane; protein-containing complex
Genetic constraint (gnomAD): Loss-of-function variants: 28 observed, 51.03 expected, observed/expected ratio (o/e) 0.55, 90% interval 0.41 to 0.75. The upper end of that interval is the gene's LOEUF score, 0.75, which puts it in group 3 of 6, group 1 being the genes least tolerant of losing a copy. Missense variants: 590 observed, 697.78 expected, observed/expected ratio (o/e) 0.85, 90% interval 0.79 to 0.9. Synonymous variants: 287 observed, 291.77 expected, observed/expected ratio (o/e) 0.98, 90% interval 0.89 to 1.09.
Homologues: Orthologues: macaque TAB1 (100% identical), chimpanzee TAB1 (99% identical), dog TAB1 (98% identical), mouse Tab1 (97% identical), rabbit TAB1 (97% identical), rat Tab1 (96% identical), pig TAB1 (96% identical), guinea pig TAB1 (95% identical), tropical clawed frog tab1 (74% identical), zebrafish tab1 (44% identical), Caenorhabditis elegans pdp-1 (12% identical), Drosophila melanogaster Pdp (12% identical). Paralogues in human: PPM1B (16% identical), PPM1N (15% identical), PDP1 (15% identical), PPM1A (15% identical), PPM1K (15% identical), PPM1D (15% identical), PPM1E (15% identical), PPM1G (14% identical), PP2D1 (14% identical), PDP2 (14% identical), PPM1H (13% identical), PPM1F (13% identical), and 4 more.
Diseases named in the same sentence as TAB1 in open-access papers:
TAB1 is named in the same sentence as 50 diseases in open-access papers, as found by Europe PMC text mining. Sharing a sentence is not in itself a finding about the gene and the disease. The quoted sentences say what the papers report.
breast carcinoma (7 papers, 2015 to 2025). "For example, activation of the TAB1/TAK1/IKKβ/NF-κB signaling axis by TGF-β is a key factor in breast cancer cell invasion." (PMID 36609391, 2023). "We detected MDM2, MDMX and TAB1 expression in 70 breast cancer tissues with IHC staining." (PMID 31892970, 2020). "Interestingly, that the recombinant, dual-target MDM2/MDMX inhibitor could reverse doxorubicin resistance via the activation of the TAB1/TAK1/p38 MAPK cascade in breast cancer cells is consistent with our result." (PMID 35335125, 2022). "We only evaluated MDM2/MDMX and TAB1 expression by IHC and collected the clinicopathological characteristics of 70 breast cancer patients in order to explore the correlations between MDM2/MDMX and TAB1 expression levels." (PMID 31892970, 2020). "Inhibition of TAK1 by RNAi knockdown of TAB1 significantly suppressed tumor growth and metastasis in vivo, suggesting that TAK1 is a potential therapeutic target for breast cancer." (PMID 27599572, 2016). "To clarify the role of TAK1 in breast cancer in vivo, we established TAK1 and TAB1 knockdown stable clones by using short-hairpin RNA (shRNA) methodology." (PMID 25557171, 2015). "In addition to this, several target proteins that have been shown to interact with TP are mostly highly expressed in breast cancer cells, such as XPB, TAB1, ADAM10, DCTPP1, Erα." (PMID 40444046, 2025). "Previous study has demonstrated that TAB1 is not expressed in breast cancer cells." (PMID 27009840, 2016). "In addition, the effect of TAK1 on the transcription repressors may be cell-type dependent because we did not see the alteration of Snail and Slug in our TAB1-inhibited breast cancer cells." (PMID 25557171, 2015). "Since TAB1 is not expressed and TAB2 in not O-GlcNAcylated in breast cancer by our previous results, the present study focus on whether TAB3 O-GlcNAcylationis participating in the metastasis of breast cancer." (PMID 27009840, 2016).
myocardial ischemia (7 papers, 2015 to 2025). A disorder of cardiac function caused by insufficient blood flow to the muscle tissue of the heart. "We used the mouse model to elucidate the role of the interaction during myocardial ischemia in vivo — a setting where p38α is known to be activated through the TAB1 interaction and to cause TAB1 phosphorylation." (PMID 30135318, 2018). "The p38α MAPK autophosphorylates its activation loop, and this reaction can be activated by a peptide fragment of TGFß-activated kinase 1 binding protein 1 (TAB1) in response to myocardial ischemia and other conditions." (PMID 36063999, 2022). "Supporting this, the recent TAB1-KI mice where TAB1-induced autophosphorylation of p38 was genetically perturbed had significantly reduced infarction volume after induction of myocardial ischemia." (PMID 33920735, 2021). "In a separate cardiac ischemia model, the TAB1-p38 interaction is upregulated in an AMPK-dependent manner." (PMID 33920735, 2021). "The autoactivation of p38α MAPK through TAB1 was observed in pathological conditions, including cardiac ischemia and heart failure and has been shown to aggravate myocardial injury (De Nicolaet al., 2018;Liet al., 2005;Shiet al., 2010;Tannoet al., 2003)." (PMID 32676538, 2019). "We also observed an almost complete abolition of TAB1 phosphorylation during cardiac ischemia, confirming that the disruption of the p38α-TAB1 complex occurs in vitro." (PMID 30135318, 2018). "During myocardial ischemia, p38α interacts with TAB1, a scaffold protein, which promotes p38α autoactivation; active p38α (pp38α) then transphosphorylates TAB1." (PMID 30135318, 2018). "A number of groups have shown that, during myocardial ischemia, TAB1 binds to and induces autoactivation of p38α, which in turn phosphorylates TAB1." (PMID 30135318, 2018). "Disrupting TAB1-p38α interaction in vivo has a protective effect during myocardial ischemia and can be achieved in vitro with small molecule inhibitors." (PMID 30135318, 2018). "Beyond NF-κB regulation, TAB1 mediates p38-mitogen-activated protein kinase (MAPK) activation via autophosphorylation, contributing to myocardial ischemia injury, while its knockdown mitigated cardiomyocyte hypertrophy." (PMID 41303324, 2025).
COVID-19 (4 papers, 2021 to 2023). A disease caused by infection with severe acute respiratory syndrome coronavirus 2. "Furthermore, The NSP5 proteases of SARS-CoV-2 could mediate the cleavage of TAB1 which point to enhance production of cytokines and inflammatory response in COVID-19 patients, demonstrating that they involved in the host innate immune response." (PMID 38072991, 2023). "Direct cleavage of IRF3 by NSP3 could explain the blunted Type-I IFN response seen during SARS-CoV-2 infections while NSP5 mediated cleavage of NLRP12 and TAB1 point to a molecular mechanism for enhanced production of cytokines and inflammatory response observed in COVID-19 patients." (PMID 33372854, 2021). "Cleavage of IRF3 and critical modulators of inflammatory pathways (NLRP12 and TAB1) was proven by proteases nsp3 and nsp5 in SARS-CoV-2 infected 293T-ACE2 cells, which was involved in the pathophysiology of COVID-19." (PMID 37801439, 2023).
ovarian carcinoma (4 papers, 2017 to 2025). A malignant neoplasm originating from the surface ovarian epithelium. "Collectively, we report for the first time that the overexpression of NF-κB1, c-Rel, and ELK1, causing the transcriptional repression of miR-134 in ovarian cancer cells, contribute towards their paclitaxel-resistance via miR-134 and that TAB1 might be a direct target of miR-134 in this process." (PMID 28206956, 2017). "Taken together, our findings demonstrated that the CD83 intracellular domain was important for its association with TAK1/TAB1 and activation of the MAPK signaling pathway, as well as CD83 function in ovarian cancer cells." (PMID 32823589, 2020). "On the other hand, CD83 stabilizes the expression of TAB1 in ovarian cancer cells upon protein degradation." (PMID 32823589, 2020). "Together, these results provide sufficient evidence to conclude that TFs of NF-κB1, c-Rel, and ELK1 transcriptionally repress miR-134 expression, thereby leading to TAB1 upregulation and contributing to ovarian cancer chemoresistance." (PMID 28206956, 2017). "We also identified TAB1 as a direct target of miR-134 in ovarian cancer cells." (PMID 28206956, 2017). "Moreover, to our knowledge, our study provides the first evidence that TAB1 is a direct target of miR-134 in ovarian cancer." (PMID 28206956, 2017). "However, whether TAB1 is effective in inducing chemoresistance to therapeutic drugs against ovarian cancer is not yet clearly understood." (PMID 28206956, 2017). "For example, In human ovarian cancer that is resistant to paclitaxel, the expression of miR-134 is suppressed by ELK1, which increases TAB1 levels." (PMID 40666290, 2025).
cardiac hypertrophy (3 papers, 2019 to 2024). "Interestingly, RNF207 was shown to interact with TAB1, a protein that activated pathways related to cardiac hypertrophy and, in another study, accumulated in nuclei and intercalated disks of isolated rat cardiomyocytes." (PMID 37723491, 2023).
non-small cell lung carcinoma (3 papers, 2017 to 2023). A group of at least three distinct histological types of lung cancer, including non-small cell squamous cell carcinoma, adenocarcinoma, and large cell carcinoma. "TAB1 was reported to promoted cell proliferation, invasion, and migration in non-small cell lung cancer." (PMID 36609391, 2023). "It is previously demonstrated that the expression level of TAB1 in non-small cells lung carcinoma tissue was significantly higher than that in tumor-adjacent normal tissue, and the TAB1 expression level was negatively related to patient prognosis." (PMID 30560887, 2018).
type 2 diabetes (3 papers, 2016 to 2021). "Since enhanced basal activity of p38 has been correlated with type 2 diabetes, it may be possible that increased O-GlcNAcylation of TAB1 is the cause of both reduced contractility of cardiac myocytes and hyperglycemia." (PMID 27314954, 2016). "The hub genes CEBPD, TP73, ESR2, TAB1, MAP 3K5, FN1, UBD, RUNX1, PIK3R2 and TNF, which might play an essential role in obesity associated type 2 diabetes mellitus was further screened." (PMID 33902539, 2021). "These hub genes were associated with progression of obesity associated type 2 diabetes mellitus and first five (CEBPD, TP73, ESR2, TAB1 and MAP 3K5) of them might be linked with targeted therapy." (PMID 33902539, 2021).
diabetic kidney disease (2 papers, 2020 to 2023). Progressive kidney disorder caused by vascular damage to the glomerular capillaries, in patients with diabetes mellitus. "Furthermore, albuminuria, the tubulointerstitial damage index and glomerular mesangial expansion index of STZ-induced diabetic nephropathy mice were decreased by TAB1 knockdown." (PMID 33044562, 2020). "In diabetic kidney disease, high glucose levels promote macrophage activation via HIF-1α activation mediated by TGF-β-activated kinase 1-binding protein-1 (TAB1), and inhibiting TAB1 alleviates kidney inflammation and disease progression." (PMID 37234412, 2023). "Western blotting, flow cytometry, qRT-PCR, ELISA, PAS staining and immunohistochemical staining were used for assessment of TAB1/nuclear factor-κB (NF-κB)/hypoxia-inducible factor-1α (HIF-1α), iNOS, glycolysis, inflammation and the clinical and pathological manifestations of diabetic nephropathy." (PMID 33044562, 2020).
Hyperglycemia (2 papers, 2016 to 2022). An increased concentration of glucose in the blood. "A recent study showed that TAB1 undergoes O-GlcNAcylation in vivo in response to hyperglycemia as well as IL-1 and osmotic stress, demonstrating that TAB1 O-GlcNAcylation is controlled by activators of TAK1 signaling." (PMID 36359905, 2022).
idiopathic pulmonary fibrosis (2 papers, 2023 to 2026). Idiopathic pulmonary fibrosis (IPF) is a nonneoplastic pulmonary disease that is characterized by the formation of scar tissue within the lungs in the absence of any known cause. "A bleomycin-induced pulmonary fibrosis model, which is the standard mouse model of lung fibrosis, was developed to demonstrate that osa-miR172d-5p suppressed lung fibrosis and downregulated Tab1 expression." (PMID 36746980, 2023). "Using a bleomycin-induced pulmonary fibrosis model, we demonstrated that osa-miR172d-5p suppressed lung fibrosis and Tab1 expression." (PMID 36746980, 2023). "Moreover, in fibroblasts and idiopathic pulmonary fibrosis models, YY1 is regulated post-translationally by the E3 ubiquitin ligase NEDD4, which ubiquitinates YY1, alters its protein stability, and thereby modulates TAB1-dependent profibrotic proliferation and extracellular matrix production." (PMID 41560817, 2026).
Insulin resistance (2 papers, 2019 to 2023). Increased resistance towards insulin, that is, diminished effectiveness of insulin in reducing blood glucose levels. "Mechanistically, FGF-1 attenuates inflammation and insulin resistance through blocking the TAK1/TAB1 interaction." (PMID 31866871, 2019). "In addition, interaction between endogenous TAK1 and TAB1 was strongly inhibited in the liver of FGF-1 treated obesity- or TNF-α-induced insulin resistance mice." (PMID 31866871, 2019). "The cytoplasmic β arrestin-2 interacts with TAB1 and blocks the interaction between TAB1 and TAK1, thereby inhibiting TAK1 activity, downstream IKKβ/NFκB and JNK/AP1 signaling, and improving diet-induced insulin resistance." (PMID 37960324, 2023).
ischemia (2 papers, 2016 to 2018). A hypoperfusion of the BLOOD through an organ or tissue caused by a PATHOLOGIC CONSTRICTION or obstruction of its BLOOD VESSELS, or an absence of BLOOD CIRCULATION. "This makes the TAB1-mediated p38α activation pathway an attractive target, since it may be a gateway to ischemia-selective inhibition." (PMID 29229647, 2018). "Since, the experiment did not directly vary TAB1 amount in ischemic heart, it can be inferred that induction of ischemia may have induced TAB1, leading to the increased p38 activation." (PMID 27314954, 2016). "However, deletion of MKK3 did not have considerable effect on p38 activation in ischemia, leading to the conclusion that TAB1 mediated autophosphorylation, instead of MKK3, may be responsible for p38 activation in ischemic heart." (PMID 27314954, 2016).
pancreatic cancer (2 papers, 2022 to 2026). "Western blotting was employed to detect the expression of p65, p-p65, p-TAK1, TAK1, TAB1, p-ERK, and ERK in pancreatic cancer cells (MIA PaCa-2) after exposure to alizarin, Gem and Gem + alizarin." (PMID 35541911, 2022).
viral infection (2 papers, 2017 to 2020). "In this study, we focused on the clinical and biological importance of p38 MAPK in viral infections, and revealed a new mechanism by which HCV infection triggers TAB1-dependent p38 activation to phosphorylate the HCV core protein to promote HCV replication." (PMID 33204339, 2020).
breast tumor (1 paper, 2015). "We showed that activated TAK1 (as indicated by phospho-TAK1) and its binding protein TAB1 are strongly expressed in breast tumor tissues (77% and 74% respectively)." (PMID 25557171, 2015).
colorectal cancer (1 paper, 2020). A primary or metastatic malignant neoplasm that affects the colon or rectum. "Moreover, knockdown of TAK1 restored the sensitivity of TAB1-overexpressing colorectal cancer cells to Sur-X-induced necroptosis." (PMID 32381104, 2020). "All these results indicated that Sur-X promoted necroptosis by interfering with the interactions between XIAP and TAB1 and subsequently destabilizing TAK1 to alleviate the inhibition of TAK1 on necroptosis in colorectal cancer cells." (PMID 32381104, 2020). "Mechanistically, it was found that apart from inducing apoptosis by disrupting the survivin-XIAP complex, Sur-X also promoted necroptosis in colorectal cancer cells by interfering with the interaction between XIAP and TAB1." (PMID 32381104, 2020). "To this end, we first confirmed the formation of the XIAP-TAB1-TAK1 complex in colorectal cancer cells by the detection of XIAP and TAK1 in co-immunoprecipitation with TAB1." (PMID 32381104, 2020). "However, TAB1 overexpression (TAB1-OE) attenuated the inhibition effects of Sur-X on colorectal cancer cells and decreased the expression of p-MLKL, which further confirmed the disruption of XIAP-TAB1 interactions by Sur-X." (PMID 32381104, 2020).
dystrophinopathy (1 paper, 2023). "Certainly, more investigations are needed in other mouse models, including DBA/2J-mdx mice, and higher vertebrates, such as the golden retriever muscular dystrophy model, to test whether overexpression of TAK1 and TAB1 ameliorates dystrophinopathy and improve muscle mass." (PMID 37071470, 2023).
esophageal cancer (1 paper, 2023). A primary or metastatic malignant neoplasm involving the esophagus. "TAB1 has also been reported associated with the progression and prognosis of esophageal cancer." (PMID 36999031, 2023).
fibrosis (1 paper, 2023). the formation of excess fibrous connective tissue in an organ or tissue in a reparative or reactive process. "Therefore, plant-derived miR osa-miR172d-5p suppressed Tab1 in the bleomycin-induced fibrosis model." (PMID 36746980, 2023). "Importantly, this study was the first to describe that Tab1 suppression could ameliorate bleomycin-induced fibrosis." (PMID 36746980, 2023).